CDK5 (cyclin dependent kinase 5)
Diseases named in the same sentence as CDK5 in open-access papers (continued):
Sharing a sentence is not in itself a finding about the gene and the disease.
cancer (continued). "Also in cancer, the majority of available notions are related to the roles proposed for CDK5." (PMID 39800748, 2025). "However, in these cancers, CDK5 also inhibits oncogenic pathways through a few substrates." (PMID 37993880, 2023). "Thus, these phosphorylation modifications of NPF and regulatory factors that can phosphorylate NPF, such as Shp1, Dyrk1A, Casein Kinase II, PAK4, SRC, ERK, Abl, Cdk5, etc., may provide targets for anti-invasive cancer therapy." (PMID 37026902, 2023). "Thus, hyperactivating CDK5 by p25 formation in cancer may be an effective approach to promote cell death." (PMID 37993880, 2023). "Finally, more than two dozen direct substrates of CDK5 have been identified in cancer to date." (PMID 37993880, 2023). "Interestingly, increased CDK5 activity was shown to be involved in several cancers." (PMID 36831133, 2023). "Furthermore, the use of small molecules to control CDK5’s subcellular localization could be a promising approach to treating cancer." (PMID 37993880, 2023). "Furthermore, while p35 overexpression is oncogenic, hyperactivation of CDK5 by inducing p25 formation results in apoptosis, which could be exploited to selectively kill cancer cells by dialing up CDK5 activity, instead of inhibiting it." (PMID 37993880, 2023). "Indeed, the impacts of Cdk5 on the hallmarks of cancer are different, such as the uncontrolled proliferative signaling and its aftermath: growth suppression, tumour promoting inflammation, invasion and metastasis, induction of angiogenesis, genomic instability and mutation." (PMID 36142566, 2022). "In addition, knockdown of CDK5 can decrease the cellular DNA damage repair ability and inhibit tumor cell growth, suggesting that inhibition of CDK5 in combination with traditional chemotherapeutic agents may be an effective strategy for cancer treatment." (PMID 35006426, 2021). "However, CDK5 may also regulate cancer metastasis of some forms of cancer, including gastric, prostate, breast, lung, pancreatic, and melanoma." (PMID 33805800, 2021). "Hence, further studies are needed to confirm the effect of CDK5 on immune, especially in cancer." (PMID 33396266, 2020). "In our study, we found that, after TOX knockdown, some proliferation and apoptosis-associated genes, such as PFKFB3, CDK5 and CKKN2A, were up- or down-regulated and most DEGs were enriched in cellular process and cancer pathways, which highlights the importance of TOX in cancer process." (PMID 31676945, 2020). "Hence, CDK5 regulation is a potential cancer therapeutic target." (PMID 33396266, 2020). "However, other groups reported that CDK5 inhibits proliferation and migration of cancer cells." (PMID 33396266, 2020). "PD-L1 constitutive expression in cancer cells may be due to several oncogenic pathways, including chromosome 9 amplification, PTEN deletions, PI3K/AKT, and EGFR mutations, MYC overexpression, CDK5 disruption, and increased PD-L1 transcription." (PMID 32824016, 2020). "Cdk5 may regulate cancer cell motility and invasion through remodeling of the cytoskeleton." (PMID 31548578, 2019). "In addition, the anti-cancer drug roscovitine, that is currently being tested in clinical trials, was recently described to regulate inflammatory processes by inhibiting different Cdks such as cyclin-dependent kinase 5 (Cdk5)." (PMID 31354714, 2019). "We found that CDK5 is rarely mutated across cancers and more importantly is not mutated in CRC." (PMID 29435174, 2018). "However, cancer genes, including CDK5 and STAT3, represent the most influential factors." (PMID 29312535, 2017). "Cdk5 takes part in DDR process mainly by phosphorylating some of the critical DDR proteins such as ataxia–telangiectasia mutated (ATM) and apurinic/apyrimidinic endonuclease 1 (Ape1), and the inhibition of this kinase activity has been proven to regulate DDR process and cancer progression." (PMID 28288624, 2017).
cancer (continued). "Cdk5 has been found to participate in several biological processes of extraneuronal activities, such as gene expression, cell migration, apoptosis, myogenesis, etc.; and pathological processes including cancer, senescence, diabetes, immune dysfunction and inflammation." (PMID 28288624, 2017). "Thus, we were interested in using the beta-catenin knowledge network to identify possible links between CDK5 and positive regulation of beta-catenin co-activator function that could be relevant to cancer." (PMID 26509276, 2015). "We hypothesized that nestin/CDK5/Rac1 signaling behaves different in early and advanced cancer." (PMID 25371063, 2015). "In addition there are many lines of evidence linking CDK5 to growth and cancer related actions." (PMID 26555036, 2015). "Previous studies also confirmed that CDK5 might be a critical player in cancer cell proliferation." (PMID 26205145, 2015). "Additionally, a series of reports reveal the importance of Cdk5 in cancer cells." (PMID 23304206, 2012). "Experimental data demonstrate that LIMK1 and CDK5 synergistically facilitate cancer metastasis through a mechanism dependent on phosphorylation and co-targeting LIMK1 and CDK5 significantly suppresses tumor metastasis." (PMID 41614944, 2026). "Dinaciclib is a pan−CDKi with nanomolar potency towards CDK1, CDK2, CDK5, and CDK9 and potent activity against a range of human cancer cell lines with promising results in preclinical safety and pharmacokinetic studies." (PMID 38254859, 2024). "We found that knockdown of ERK5 and CDK5 synergize in suppressing cancer cell proliferation and induce apoptosis of A549 cells only when combined, confirming a role of ERK5 and CDK5 in promoting the proliferation and survival of NSCLC cells." (PMID 39271958, 2024). "While CDK5 should certainly have distinct tissue-specific substrates, regulatory mechanisms for many of its common substrates may be similar in different tissues, analysis of which should aid in identifying critical signaling nodes, particularly for each tissue-specific cancer." (PMID 37993880, 2023). "Based on these results, CDK1, CDK2, CDK4, CDK5, and CDK7 are the top 5 CDKs that are highly expressed in cancer tissues compared to normal tissues." (PMID 37311884, 2023). "CDK5 is able to induce the phosphorylation of ATM at Ser729, to activate DNA damage repair to promote cancer proliferation." (PMID 35006426, 2021). "Besides, since CDK5 is a target present in nerves, the neurological side effects of concern can be minimised through a strategy that prevents the passage of the blood-brain barrier, and a study of CDK5 therapy in carcinomas where nerves are involved in the growth and progression of cancer." (PMID 33396266, 2020). "To determine the potential contribution of inhibiting CDK3 and CDK5, as compared to CDK2 and CDK9, we analyzed data publicly available from genome-wide CRISPR-Cas9 screens in >700 cancer cell lines (from the Cancer Dependency Map project)." (PMID 32645016, 2020). "We initially examined Cdk5 protein expression in the surgically resected CRC tissues and matched adjacent histologically cancer-free specimens from each patient." (PMID 33488528, 2020). "CDK5, a member of CDK family, was considered to play an important role in numerous cancer-related biological behaviors such as cell proliferation, metastasis, angiogenesis, and immune escape." (PMID 31363080, 2019). "This work not only unveils the mechanism of Cdk5 in regulating cell migration and invasion through ADD1, but also highlights the role of ADD1 in cancer progression." (PMID 31548578, 2019). "In head and neck squamous cell carcinoma, aberrant over-expression of Cdk5 significantly induces tumor cell motility and epithelial mesenchymal transition (EMT), which is considered as a pivotal process of cancer metastasis." (PMID 28288624, 2017). "Here we describe the regulatory mechanisms of Cdk5, its controversial roles in apoptosis and focus on its links to DDR and cancer." (PMID 28288624, 2017).
cancer (continued). "The other distinct class includes CDK inhibitors that are more selective for CDK1 and CDK2 as well as the transcriptional CDKs (CDK5, CDK7, and CDK9), and these drugs are being more widely studied in cancers including triple-negative breast cancer." (PMID 28107181, 2017). "Dinaciclib, a potent CDK2 inhibitor (as well as CDK1, CDK5, and CDK9 inhibitor) that is currently in clinical trials for several cancers, was used to target the cyclin E/CDK2 pathway." (PMID 28107181, 2017). "Here we focus on the regulation of Cdk5, its dual roles in apoptosis, and its links with DDR and cancer development and treatment." (PMID 28288624, 2017). "Thus, CDK5 might be heterogeneously expressed in different cancers." (PMID 26860827, 2016). "CDK5 is also a mediator of TGF-β1-induced epithelial-mesenchymal transition and migration in cancer cells, and is involved in tumor formation." (PMID 27557521, 2016). "Downstream signaling of nestin [cyclin-dependent kinase 5 (CDK5) and Ras-related C3 botulinum toxin substrate 1 (Rac1)] functions in cancer to modulate cellular behaviors." (PMID 25371063, 2015). "Dinaciclib, a novel small molecule inhibitor of CDK1, CDK2, CDK5 and CDK9, is assessed in clinical trials for the treatment of several types of cancers." (PMID 25962959, 2015). "Functional analysis of the upregulated genes mapped to cell proliferation and cancer related canonical pathways such as ‘ERK/MAPK signaling’, ‘CDK5 signaling’, and ‘14-3-3-mediated signaling’." (PMID 23216862, 2012). "Results revealed that the upregulation of LIMK1 or CDK5 shared similar activated/inhibited signaling pathways including focal adhesion, ECM‐receptor interaction, cell cycle, and some critical signaling pathways in cancer." (PMID 40476449, 2025). "Cdk5 inhibitor roscovitine is used for cancer research but not yet proven for neurological diseases." (PMID 38842132, 2024). "To further test this hypothesis, we assessed the effect of pharmacological inhibition of ERK5 (XMD8-92) and CDK5 (Seliciclib) in a panel of NSCLC cancer cells (A549, A427 and H460) bearing mutKRAS." (PMID 39271958, 2024). "Despite the extensive studies that correlating CDK5 expression and cancer occurrence, drug therapies that selectively inhibit CDK5 were not available until very recently." (PMID 37887415, 2023). "In contrast, CDK5 was rarely mutated among cancers and, more importantly, was never mutated in CRC, indicating that CDK5’s contribution to CRC oncogenesis was due to its high expression rather than mutation." (PMID 37511490, 2023). "The CDK1, CDK5, CDC20, CCNA2, CCNB1 and CCNB2 expression levels (tumor sample: n = 369 vs. normal sample: n = 160) were upregulated in HCC group compared with the non-carcinoma group (Analysis by GEPIA dataset)." (PMID 36605491, 2023). "The most prominent Cdk5 inhibitor, roscovitine, has proven to be a useful tool in neuroscience and has also yielded promising results in the treatment of various cancers but has not been approved for use in neurological conditions." (PMID 35645825, 2022). "We found similarities in pathways and upstream regulators of FOXO3-deficient macrophages with HFD obese mice colon associated with inflammation (IL-1A, IL-1B, IL-6, IL-8 signaling), growth (ILK signaling, CDK5 signaling, VEGF signaling) and cancer (cAMP-mediated signaling)." (PMID 35323693, 2022). "Cyclins and cyclin-dependent kinases (CDKs) are major effectors of the cell cycle with key role in cancer where our data shows downregulation of key cell-cycle proteins such as cyclin D1 and Geminin and mRNA levels of CCNE1, CCNF, CDK1, CDK2 and CDK5." (PMID 35902556, 2022).
cancer (continued). "Growing evidence indicates that Cdk5 has important non-neuronal functions in cancer progression, insulin secretion, and immune responses." (PMID 35421092, 2022). "This compound is, by far, the most effective inhibitor of CDK5/p25 (IC50 = 160 nM), as shown by numerous studies using this compound as a potential drug against cancer, neurodegenerative or viral diseases, inflammation, polycystic kidney disease (PKD) and glomerulonephritis." (PMID 33802080, 2021). "Because CDK5 inhibitors are cytotoxic or apoptotic against diverse normal or cancer cell lines, the non-cytotoxic concentrations of Ro-3306, A-674563, AT7519, and roscovitine were chosen for screening their adiponectin production-enhancing activity." (PMID 32054125, 2020). "TCGA pairwise analysis with key pathway proteins indicated a notable correlation between the cell cycle CDKs 2 and 4 (negative) and CDK5 (positive) with mitochondrial antioxidant proteins in all three cancer types." (PMID 32033319, 2020). "Many of these conclusions were based on experiments which employed treatment of cell lines representing different normal or cancer types with pan-CDK inhibitors, or employed overexpression of dominant-negative CDK5 constructs, or expression of anti-CDK5 siRNAs or shRNAs." (PMID 31910742, 2020). "Recently, the effect of CDK5 on cytoskeletal elements has been expanded to non-neuronal cells such as cancer cells." (PMID 33396266, 2020). "The role of Cdk5 in the proliferation of tumor cells is not clear, but many studies have demonstrated its implication in cancer migration, invasion, and anchorage-independent growth." (PMID 31614664, 2019). "Taken above, CDK5 might be used as a potential biomarker in predicting prognosis of NSCLC patients, and regarded as a novel target for anti-cancer therapies." (PMID 31496920, 2019). "To investigate whether CDK5 was also involved in HCC cell migration and invasion, we overexpressed GFP-tagged CDK5 and GFP-tagged CDK5-KD (kinase death) in Huh7 cancer cell lines." (PMID 31272499, 2019). "CDK5 phosphorylates a diverse list of substrates, implicating that it can regulate various cellular processes including the function of c-MYC, which is a crucial transcription factor in cancer." (PMID 31496920, 2019). "Indeed, elevated activation of Cdk5 and PKCδ and increased phosphorylation of ADD1 at T724 and S726 were detected in the highly metastatic cancer cells." (PMID 31548578, 2019). "Our and others results together suggest that Cdk5 may be a critical effector to transmit the EGF signaling, leading to reorganization of the actin cytoskeleton and cell migration in cancer cells." (PMID 31548578, 2019). "The function and substrates of CDK5 are well-studied in post-mitotic neurons; however, the role of CDK5 in cancer is not very well understood." (PMID 31534152, 2019). "However, the knowledge of the biological and pathological functions of Cdk5 in DDR and cancer is still limited, more efforts need to be taken to explore and exploit this kinase better." (PMID 28288624, 2017). "Taken all together, the up-regulation of Cdk5 is a result of DNA damage stimulation and in turn induces DNA repair through STAT3-mediated up-expression of Eme1, which may confer cancer cells resistance to chemotherapy treatment." (PMID 28288624, 2017). "However, recent reports demonstrate that CDK5 takes part in the stress response to reactive oxygen species and participates in NOXA regulation in both neural and cancer cell types." (PMID 26606677, 2015). "Also known as CYC202 or seliciclib, this purine analog primarily inhibits CDK2 and CDK5, as well as CDK1, CDK7 and CDK9 in several forms of human cancers." (PMID 25625291, 2015). "CDK5 is a serine/threonine kinase that is highly expressed in the brain and regulates neuronal function but its role in cell cycle and cancer has not been well explored." (PMID 25900242, 2015).
cancer (continued). "We found that CDK5 was inhibited only in T24 and UMUC3 cells, and the inhibitory effect of CDK5 was more obvious in the presence of SDA, indicating that NSGEP only driven the expression of CRISPR-CasΦ only in cancer cells and the SDA could improve the efficiency of CRISPR-CasΦ." (PMID 38724931, 2024). "Inhibition of CDK5 elevated the expression of FBXO22 and subsequently inhibited PD-L1 protein levels, indicating that CDK5 was an upstream regulator of FBXO22 and that CDK5 inhibitors could increase the efficacy of immunotherapy in cancer cells." (PMID 36733484, 2023). "However, further investigations have identified expression of p35 and a plethora of divergent roles for CDK5/p35 in many non-neuronal cell types, including cancer cells and immune cells." (PMID 37377891, 2023). "There is not much evidence regarding the impact of CDK5 on cancer metabolism." (PMID 33396266, 2020). "The possibility of whether Cdk5 targets WAVE proteins to promote lamellipodia in cancer cells or other non-neuronal cells remains to be tested." (PMID 31548578, 2019). "We could not detect expression of the p35 regulatory subunit of CDK5, which is reportedly expressed primarily in postmitotic neurons, although a role in cancer is emerging." (PMID 29063678, 2018). "Cdk5 is a serine/threonine kinase that is highly expressed in the central nervous system (CNS) and is essential for neuronal development and function, but its role in the periphery and in cancer is not well explored." (PMID 26755662, 2016). "For each cancer cell line, 6 groups of 10 mice were treated for 4 weeks as follows: 1) DOPC nanoliposomes, 2) control siRNA-DOPC, 3) CDK5 siRNA-DOPC, 4) paclitaxel, or 5) a combination of control siRNA-DOPC plus paclitaxel, or 6) a combination of CDK5 siRNA-DOPC plus paclitaxel." (PMID 26146988, 2015). "Given Cdk5’s established role in regulating the cytoskeletal organization, cell adhesion, and motility, it is plausible that it could influence CAF activation, extracellular matrix deposition, or secretion of pro-tumorigenic factors that drive cancer progression." (PMID 41369365, 2025). "Therefore, it was the aim of the present study to determine whether USF2 can be phosphorylated by CDK5 and to investigate the impact of CDK5-dependent USF2 phosphorylation on cell proliferation and migration in human cancer cells lacking CDK5." (PMID 31013770, 2019). "However, in the context of HD pathogenesis, since CDK5 may have critical roles for normal brain function, it would be better to maintain a certain level of CDK5 activity rather than totally inhibiting its activity, like in cancer treatment." (PMID 39596381, 2024).